METTL3 (methyltransferase 3, N6-adenosine-methyltransferase complex catalytic subunit)
Diseases named in the same sentence as METTL3 in open-access papers (continued):
Sharing a sentence is not in itself a finding about the gene and the disease.
cancer (continued). "The research about the role METTL3 in various cancers revealed that METTL3 has great potential for clinical application by serving as a new diagnostic/prognostic/treatment target." (PMID 31921660, 2019). "METTL3 (methyltransferase-like 3)-catalyzed RNA methylation is required for cancer development, whereas the role of METTL14 varies with cancer types." (PMID 31735169, 2019). "In contrast, METTL3 partitioned between the nucleus and the cytosol, resembling recent observations in human cancer cells and mouse embryonic stem cells." (PMID 30456371, 2018). "Among the regulators of m6A, METTL3, the crucial methyltransferase of m6A, plays a promotor in most of cancers." (PMID 30062093, 2018). "METTL3 plays an oncogenic role in cancer cells, promoting the translation of cancer genes through interactions with the translation initiation machinery." (PMID 29061143, 2017). "A recent study demonstrated that METTL3 enhances translation in cancer cells independently of m6A modification." (PMID 28297667, 2017). "STM2457, a highly efficient METTL3 inhibitor, can inhibit METTL3 activity and may serve as a potential therapeutic strategy in cancers." (PMID 41875089, 2026). "Therefore, the development of drugs to inhibit Mettl3 holds great promise as a potential therapeutic approach in cancer treatment." (PMID 41517663, 2026). "This indicated that the transcription of METTL3 was activated in cancer cells." (PMID 39800682, 2025). "METTL3 can modulate the immune response in various cancers, and similar mechanisms may be at play in OS." (PMID 40052548, 2025). "The subcellular localization of METTL3 plays a critical role in cancer metastasis." (PMID 39802639, 2025). "However, our research indicates that METTL3 expression in cancer cells makes PDACs more permissive to VSV and potentially other oncolytic viruses." (PMID 40214229, 2025). "Similarly, METTL14 also plays a role in cancer as METTL3, which also promotes the recognition and binding of DGCR8 to m6A-modified pri-miRNAs, thus facilitating miRNA maturation." (PMID 40734692, 2025). "METTL3 may contribute to the development of resistance to chemotherapy and/or radiation‐based cancer treatments." (PMID 40919129, 2025). "METTL3 and the m6A modification are involved in various cancers through influencing various cancer-related cellular processes, like tumorigenesis, stemness of cancer cells, metastasis, and chemotherapy resistance." (PMID 41321637, 2025). "Gene Set Enrichment Analysis (GSEA) showed that MYC targets, mitotic spindle, G2M checkpoint, and glycolysis, all of which are hallmarks of cancer cells, were significantly activated in the Mettl3 cKO group, confirming accelerated tumorigenesis after hepatic METTL3 knockout." (PMID 40103332, 2025). "Due to different mechanisms, METTL3 can also play different roles in the same cancer." (PMID 41256854, 2025). "We demonstrate here that the cellular response to downregulated METTL3 dramatically upregulates ISGs, which may stunt cancer cell proliferation and contribute to apoptosis." (PMID 40214229, 2025). "METTL3 inhibition has been shown to induce an anti-cancer immune response and it has been suggested, therefore, that METTL3 inhibitors may complement immunomodulatory therapies, including anti-PD1 therapy." (PMID 41310336, 2025). "Our study elucidates the link between nucleotide metabolism and RNA epigenetics in tumorigenesis through the PRPS2-MAT2A-WTAP/METTL3/METTL14 axis, providing potential insights for drug design and discovery in cancers associated with PRPS2 abnormalities, such as lung adenocarcinoma." (PMID 40295500, 2025). "Dysregulation of m6A machinery, including methyltransferases (METTL3, METTL14), demethylases (FTO, ALKBH5), and m6A readers (YTHDFs, IGF2BPs), has been implicated in oncogenesis, immune evasion, and therapy failure in multiple cancers, including HNSCC." (PMID 41624157, 2025).
cancer (continued). "In particular, METTL3 plays a cancer‐promoting role in EC progression; however, the specific mechanism remains unclear." (PMID 39980152, 2025). "In addition, METTL3 has been identified as an important promoter of cancer progression and is highly expressed in esophageal cancer." (PMID 40356985, 2025). "We propose that, for this reason, it may be favorable for cancer cells to upregulate genes, such as METTL3, that aid in evading cancer immunosurveillance." (PMID 40214229, 2025). "A reduction in m6A levels, caused by the loss of METTL3, impairs the EMT process in cancer cells." (PMID 40919129, 2025). "It indicated that METTL3 negatively regulated the cilia elongation in cancer cells." (PMID 39535388, 2025). "Aberrant expression of METTL3 has been extensively reported in human cancers." (PMID 41321637, 2025). "O-glycosylation proteomics have indicated that METTL3 O-GlcNAcylation may occur; however, the implications of this modification in cancer remain enigmatic." (PMID 40651967, 2025). "In contrast, METTL3, as a methyltransferase, plays a pro-cancer role in AML by increasing the half-life of ITGA4 mRNA through m6A methylation, thereby elevating ITGA4 protein levels and facilitating chemoresistance through enhanced AML cell homing and engraftment." (PMID 40271153, 2025). "METTL3 exhibits a dual role in cancer, highlighting its highly environmentally dependent function." (PMID 41256854, 2025). "Additionally, BUB1 promotes GC cell proliferation and metastasis through METTL3-mediated m6A methylation, highlighting its critical role in both mitosis and cancer progression." (PMID 40949882, 2025). "However, prior studies have primarily investigated the role of METTL3 in established HCC using cancer cell lines or xenograft models." (PMID 40103332, 2025). "METTL3 is a key protein for m6A methylation in various types of cancers." (PMID 39820521, 2025). "In addition, research on human cancer cell lines and mouse models has established METTL3 as a potential novel anticancer target." (PMID 41245600, 2025). "Targeting m6A and METTL3 may offer new strategies by affecting cancer cell proliferation, migration, and survival." (PMID 39802639, 2025). "Inhibiting METTL3 or an m6A reader could, in principle, reduce metastatic seeding in cancers where m6A drives metastasis." (PMID 41301491, 2025). "The expression of METTL3 is dysregulated in cancer through different mechanisms." (PMID 39800682, 2025). "TCGA database revealed that METTL3 was significantly upregulated in various cancer types." (PMID 39990661, 2025). "METTL3, as an oncogene, influences the initiation and progression of various cancers." (PMID 40175350, 2025). "Furthermore, METTL3 mediates the m6A modification of circIGF2BP3, highlighting the intricate interplay between RNA modifications and immune regulation in cancer." (PMID 40279954, 2025). "LncRNA and related genes and their signaling pathways may be effective mechanistic targets for cancer treatment targeting METTL3." (PMID 41256854, 2025). "Preliminary studies have explored cancer treatments targeting the METTL3-METTL14 complex." (PMID 39155349, 2024). "In conclusion, we reported a novel mechanism of METTL3 desensitization to ferroptosis via regulating TFRC, and an appropriate reduction of METTL3 might sensitize cancer cells to ferroptosis-based therapy." (PMID 38221933, 2024). "In recent years, targeting METTL3 to alleviate cancer progression has attracted much attention." (PMID 38291427, 2024). "Thus, further investigation into the effect METTL3 inhibition in the context of immunotherapy for human cancers is warranted." (PMID 39568154, 2024). "This suggests that the large differences in DNA binding sites observed in senescent or cancer cells may be due to partial dissociation of the METTL3-METTL14 complex or redundancy in the protein abundance of METTL3 compared to METTL14." (PMID 38965238, 2024). "Emerging evidence suggested that METTL3 played a key role in various cancers." (PMID 38331776, 2024).
cancer (continued). "Methyltransferase-like 3 (METTL3), the core component of N6-methyladenosine (m6A) writer, is frequently associated with abnormalities in the m6A epitranscriptome in different cancer types, impacting both cancer cells and the surrounding TME." (PMID 38322265, 2024). "Furthermore, existing research suggests a mutual regulatory relationship between METTL3 and Snail in various types of cancer." (PMID 38605400, 2024). "However, emerging evidence also suggests that METTL3 plays catalytic activity-independent functions to promote the translation of target genes in certain types of cancers, such as LUAD and GC." (PMID 38322265, 2024). "These inhibitors demonstrate the therapeutic potential of targeting METTL3 in diseases like cancer." (PMID 39459530, 2024). "In addition to METTL3, other regulators of m6A dynamics are also targeted by various miRNAs in cancer." (PMID 39087001, 2024). "Studying whether METTL3 affects T cell activation, proliferation, and memory formation could potentially identify targets to enhance immune responses against infections or malignancies." (PMID 39416774, 2024). "Our previous research showed that forced METTL3 expression increases miR‐1246 levels in cancer cells, but uncertainty still exists on whether METTL3 contributes to exosomal miR‐1246 in CRC." (PMID 38342611, 2024). "This may suggest to us that METTL3 plays diametrically opposite roles in different signaling pathways or different cancer subtypes." (PMID 38711100, 2024). "It remains unclear whether the suppressive function of METTL3 on TANs is PTC-specific or generally applicable to most cancer types, which requires further investigation." (PMID 38322265, 2024). "METTL3, plant viruses, cancer progression and IFN-I may still be research hotspots and trends in the future." (PMID 38238848, 2024). "Further research is imperative to validate current results and gain insights into the mechanisms governing METTL3 translocation to the cytoplasm of cancer cells and whether similar mechanisms also operate in normal cells." (PMID 38444581, 2024). "Our experimental data also suggested that the METTL3/miR‐196a/GAS7 axis may be a promising therapeutic target for NSCLC or other cancers." (PMID 38370374, 2024). "Among these regulators, METTL3, a crucial “writer,” has been widely reported in various cancers." (PMID 39473907, 2024). "Also, piRNA-31106 enhances the m6A modification and accelerates the expression of METTL3 to promote cancer progression." (PMID 38075202, 2024). "METTL3 downregulates the expression of splicing factors and is overexpressed in cancer tissue." (PMID 39678510, 2024). "In HRR-deficient cells, such as CML, PARPi treatment in combination with METTL3 inactivation may induce a "synthetic lethality" effect, where the combined inhibition of two DNA repair pathways becomes lethal to the cancer cells." (PMID 39085650, 2024). "Suppression of METTL3 via miRNA-33a leads to decreased cancer cell proliferation." (PMID 38075202, 2024). "METTL3 expression in cancer cells is regulated by various mechanisms." (PMID 38166703, 2024). "For example, small molecule inhibitors or RNA-based therapies could be developed to downregulate METTL3 in scenarios where its overexpression leads to pathological angiogenesis, such as in cancer or AS." (PMID 39834386, 2024). "With the research on the regulation, function, and mechanism of METTL3 in cancer, multiple pathways of cancer affected by METTL3 have been discovered, mainly focusing on cell proliferation, cell death resistance, invasion and metastasis, angiogenesis, metabolic disorders, and immune 41,42." (PMID 39132158, 2024). "The utilization of METTL3 as a biomarker could revolutionize early detection and personalized treatment strategies for a multitude of diseases, particularly cancers." (PMID 39416774, 2024). "In most cancers, high METTL3 expression predicts a poor prognosis." (PMID 38166703, 2024).
cancer (continued). "It would be of great interest to know whether METTL3 inhibitors could effectively kill cancer cells or boost ICBs’ efficacy in solid tumors." (PMID 38322265, 2024). "Similarly, in glioblastoma, METTL3 promotes tumor growth and self-renewal of cancer stem cells through m6A modification of SOX2 mRNA." (PMID 39728691, 2024). "This level of contradictory might attribute to the different functions of METTL3 in cancer and immune cells, underscoring the complexity of targeting METTL3 in cancer immunotherapy." (PMID 38545841, 2024). "In conclusion, this study found a potential correlation between METTL3 and cuproptosis in tumorigenesis and progression, which may provide new insights and targets for cancer prevention and treatment." (PMID 38429907, 2024). "In this study, both in vitro and in vivo experiments demonstrated that AR extract could downregulate METTL3 in cancer cells and reduce the m6A modification level of total RNA." (PMID 39247584, 2024). "As an m6A methyltransferase, METTL3 has a crucial role in cancer." (PMID 39054967, 2024). "Additionally, RNA sequencing found that genes enriched in m6A-regulated genomes in METTL3-silenced GBM cell lines are related to cancer pathways, including the apoptosis signaling pathway." (PMID 39473440, 2024). "Since circ1662 is positively associated with METTL3 and YAP1 protein expression, it was suggested that circ1662 could be employed as a biomarker to identify cancer metastasis." (PMID 39136000, 2024). "Additionally, recent findings have linked TBP to m6A modifications, showing that TBP can influence m6A methylation processes by promoting the expression of key m6A writers such as METTL3, which enhances RNA stability and translation in cancer cells." (PMID 39434688, 2024). "Thus, METTL3 has emerged as an attractive drug target for anti-cancer and anti-viral therapy development." (PMID 37609305, 2024). "Targeting METTL3 as a novel therapeutic and prognostic marker and developing highly specific inhibitors hold great promise for improving patient prevention, treatment, and survival rates in future clinical applications for these cancers." (PMID 39295872, 2024). "In addition to METTL3, METTL14 has also been shown to enhance tumorigenesis and be associated with poor prognosis in several types of cancers." (PMID 39006762, 2024). "Given the different mechanisms of METTL3 action in different diseases, we suspected that it might be a valuable biomarker for identifying cancer-impeded ferroptosis and LC." (PMID 38221933, 2024). "The miRNAs‐METTL3 regulatory mechanism also participates in cancer cell death control." (PMID 36162823, 2023). "Most research studies on the m6A writer METTL3 or METTL14 indicate their oncogenic roles in cancer." (PMID 37612540, 2023). "An increasing number of studies have shown that METTL3 promotes cancer cell metastasis." (PMID 36348020, 2023). "Besides, in all the 32 cancer types of the TCGA database, METTL3 and DDX23 demonstrated significantly positive correlations." (PMID 36977668, 2023). "These two contradictory effects of METTL3 on anti-PD-1 treatment might be attributed to differences among cancer types, as well as distinct regulatory mechanisms." (PMID 37965577, 2023). "According to the results of cell phenotype assays, the JAK1-STAT3 signaling downstream effectors, including VEGFA and CCND1, were screened out and their functions were uncovered in cancer cells, but themselves were also reported as METTL3-modified targets in a recent study." (PMID 38001065, 2023). "Moreover, METTL3 relies on m6A modification to regulate some important metastasis-related transcription factors and promote the metastasis of various cancers." (PMID 37996892, 2023). "However, emerging evidence suggests that METTL3’s involvement extends beyond gene regulation and encompasses drug resistance in various cancer types, including GC." (PMID 37822880, 2023).
cancer (continued). "In GC, METTL3 could not only facilitate cancer progression via m6A-modified RNAs but also bind to numerous non-m6A-modified RNAs." (PMID 39872957, 2023). "Although a series of inhibitors against eraser proteins show potential anti-cancer effects, METTL3, the core factor of the MTC, may be the ideal target in the m6A network." (PMID 37015927, 2023). "To explore whether Sul has an anti-cancer effect by inhibiting METTL3, we treated the cells overexpressing METTL3 with Sul." (PMID 38025760, 2023). "In addition, we found that most studies suggest that METTL3 is not only correlated with the malignant transformation, but also activated in the onset of cancer metastasis." (PMID 37095108, 2023). "As for which function mediated by METTL3, m6A writer or transcription regulator, dominated cancer cell biological process, and whether this mechanism is universal among other cancer types indeed has exceeded our current study." (PMID 38001065, 2023). "Previous studies have revealed that METTL3 plays a role in various cancers." (PMID 35785826, 2023). "Hence,the role of METTL3 in this type of cancer needs to be explored moredeeply due to currently opposite pieces of evidence." (PMID 36692498, 2023). "How could METTL3 plays paradoxical roles in the same cancer type needs to be carefully investigated and addressed." (PMID 37915103, 2023). "Since RNA methylation regulates the expression of various genes involved in cancer cell proliferation, METTL3 might regulate cancer initiation and progression." (PMID 36835633, 2023). "Importantly, it is feasible to treat cancer and other diseases by using METTL3 inhibitors in combination with other therapies." (PMID 37344779, 2023). "Moreover, we employed TIMER2 to examine the potential correlations between METTL3 expression and the infiltration levels of individual immune cell types across various cancers in TCGA." (PMID 38012755, 2023). "However, the regulatory effects of m6A on cancer microenvironment is controversial, especially for the roles of METTL3 and ALKBH5 in immune cells and non‐immune cells." (PMID 36260366, 2023). "In this study, we originally investigated the role of METTL3 in various cancers." (PMID 38012755, 2023). "Since it is well known that the Hippo pathway is involved in cancer development, we predicted that METTL3 could mediate m6A modification of LATS1 and further affect the Hippo pathway." (PMID 36609396, 2023). "Depending on the different m6A-modified RNA targets, the role of the METTL3/14 complex may be contradictory in some cancer models, as opposite effects have been reported in different studies." (PMID 37612540, 2023). "The overexpression of METTL3 was observed in most tumors compared to adjacent normal tissues, and this upregulation was linked to poor overall survival (OS) and disease-free interval (DFI) in several cancer types, particularly in LIHC." (PMID 38012755, 2023). "The relevance between these genes and METTL3 has been reported in other malignant tumors, and its specific mechanism in PCa may be discussed later by our group." (PMID 37095108, 2023). "Moreover, depletion of METTL3 markedly enhanced the sensitivity of mouse xenografts and cancer cells to DNA damage treatment." (PMID 37002245, 2023). "Furthermore, in GC, higher expression of METTL3 promotes cancer cell metastasis in vivo and is predictive of poor prognosis in GC patients, which is possibly through the m6A modified stabilization of the zinc finger MYM-type containing 1 (ZMYM1) mRNA." (PMID 37015927, 2023). "In addition to METTL3, other m6A regulators are also key targets for treating cancers with abnormal m6A levels." (PMID 37063421, 2023). "Taken together, the data imply that METTL3 may be engaged in multiple common cancer-related pathways, thus performing pro-oncogenic activities in PCa cells." (PMID 37675218, 2023). "METTL3 enhanced cancer cell proliferation by inducing the methylation of USP7." (PMID 36835633, 2023).